POSTN (periostin)
Diseases named in the same sentence as POSTN in open-access papers (continued):
Sharing a sentence is not in itself a finding about the gene and the disease.
nasal polyps (continued). "Initially, researchers established mouse model and found periostin might play a protective role in the development of eosinophilic chronic rhinosinusitis with nasal polyps." (PMID 32954441, 2021). "The studies revealed an increased level of POSTN, IL-4 gene expression and a decreased level of COX-2 gene expression that may be associated with the development of chronic rhinosinusitis with nasal polyps." (PMID 25573836, 2015). "We identified that there is a positive correlation of periostin and tenascin C with MMPs and found that periostin and tenascin C could stimulate the ex vivo expression of MMPs mainly in different cells derived from nasal polyps, periostin in fibroblasts and tenascin C in epithelial cells." (PMID 34504680, 2021). "We previously found that IL‐4 and IL‐13 could induce periostin expression in nasal polyps." (PMID 34504680, 2021). "Periostin induces the myofibroblast differentiation of nasal fibroblasts, and this process, along with ECM accumulation, plays a role in the formation of nasal polyps." (PMID 37046572, 2023). "However, within nasal polyps, if and how periostin induces the expression of MMPs is still unknown." (PMID 34504680, 2021). "Given the roles of periostin and tenascin C in promoting the expression of MMPs in CRSwNPs, our results indicate that anti‐periostin or anti‐tenascin C treatment might be able to inhibit tissue remodeling within nasal polyps, which still needs to be further verified by in vivo animal studies." (PMID 34504680, 2021). "ECRS patients with nasal polyps exhibit higher periostin and POSTN mRNA levels than those without nasal polyps, reflecting their involvement in Th2-driven inflammation." (PMID 40607434, 2025). "POSTN+ fibroblasts showed a gradually increasing trend among the CM, UT, and NP groups, indicating that the two cell types (POSTN+ fibroblasts and ADGRB3+ fibroblasts) may play a mutual role in the occurrence and development of nasal polyps." (PMID 38280891, 2024). "In the presence of nasal polyps, serum POSTN levels were higher even in the non-ECRS group than in healthy controls." (PMID 30061580, 2018). "Moreover, the POSTN expression was significantly higher in those patients with CRS and nasal polyps than in those patients with allergic rhinitis." (PMID 25573836, 2015). "In rhinology, periostin has been studied extensively for its role in Th2-mediated inflammation, particularly in conditions like chronic rhinosinusitis (CRS) and its subtypes, including eosinophilic chronic rhinosinusitis (ECRS) and chronic rhinosinusitis with nasal polyps (CRSwNP)." (PMID 39728072, 2024). "As far as it concerns CRS, there is clear evidence that in subjects with bilateral nasal polyposis, nNO is reduced because of sinus ostium block; other biomarkers have been studied in this condition (in particular, pendrin and periostin), but, nowadays, they have no clear role in clinical practice." (PMID 31731479, 2019). "The aim of the study was to determine the expression of IL-5, POSTN and IL-33, at the gene and protein levels, in eosinophilic CRS with nasal polyps (CRSwNP) and without nasal polyps (CRSsNP), and to correlate this expression with clinical severity." (PMID 35752781, 2022). "The purpose of this paper was to evaluate the level of Cyclooxygenase-2 (COX-2), Periostin (POSTN) and Interleukin-4(IL-4) gene expression in patients with chronic rhinosinusitis with nasal polyps, without polyps and with a nasal septum deviation." (PMID 25573836, 2015).
keloid (28 papers, 2012 to 2026). An irregularly shaped, elevated mark on the skin caused by deposits of excessive amounts of collagen during wound healing. "Consistent with previous research, we observed an increased proportion of POSTN+ mesenchymal fibs in keloids, closely associated with ECM production." (PMID 39902627, 2025). "Another interesting discovery was that mesenchymal fibroblasts play a crucial role in the overexpression of collagen in keloids via POSTN periostin (POSTN), a protein encoded by the POSTN gene." (PMID 39895409, 2025). "The POSTN‐positive subset is associated with excessive ECM production in keloids, while the IGFBP2‐positive subset, more prevalent in normal skin, exhibits anti‐fibrotic characteristics." (PMID 39902627, 2025). "We identified skeletal system development, ossification, and osteoblast differentiation-associated genes, such as COL11A1, COMP, and POSTN, which were significantly increased in keloid mesenchymal fibroblasts." (PMID 34140509, 2021). "POSTN, which encodes periostin, plays an important role in keloid formation and increases collagen expression in keloid." (PMID 34140509, 2021). "Specific to keloids, periostin is associated with promoting the ability of keloid fibroblasts to migrate and invade surrounding tissues in hypoxia." (PMID 31440236, 2019). "POSTN is an important gene involved in keloid formation and is associated with collagen expression." (PMID 38622256, 2024). "The results of the present study demonstrated that periostin-induced angiogenesis underlies the pathology of keloids and the level of periostin may affect the process of hyperplasia and regression." (PMID 25369801, 2015). "This study has uncovered the cellular diversity and molecular mechanisms of keloids through single‐cell and ST analysis, identifying the key roles of POSTN‐positive and IGFBP2‐positive fibroblast subsets." (PMID 39902627, 2025). "This reinforces the potential role of POSTN in keloid development and supports its consideration as a candidate therapeutic target." (PMID 41278551, 2025). "In conclusion, our study identifies BMP4, WNT5A, and POSTN as novel and consistently upregulated hub genes in keloids, potentially acting at the nexus of mechanosignaling, inflammation, and matrix remodeling." (PMID 41278551, 2025). "Another hallmark of PIEZO2‐positive cells was the presence of both POSTN and PIEZO2‐positive cells, spreading from the lymphatic vessels into the dermal interstitium of keloid tissue." (PMID 40742741, 2025). "Among them, POSTN was significantly upregulated in keloid samples (p < 0.01), consistent with its role in ECM remodeling and fibroblast activation." (PMID 41278551, 2025). "Subsequently, three of these genes (BMP4, POSTN, and WNT5A) were found to be significantly associated with keloids." (PMID 41278551, 2025). "Higher expression levels of COL1A2, PIEZO2, and POSTN were observed in the keloid group compared with the lymphedema group." (PMID 40742741, 2025). "Nevertheless, PPI network analysis and subsequent validation using the independent GSE158395 dataset consistently identified BMP4, WNT5A, and POSTN as top hub genes significantly upregulated in keloid tissues." (PMID 41278551, 2025). "ScRNA-seq was performed to analyse keloids and revealed that the percentage of a fibroblast subpopulation expressing mesenchymal cell markers, such as POSTN, COMP, COL11A1, COL12A1, and COL5A2, was substantially increased." (PMID 35722137, 2022). "Previous studies reported that POSTN was overexpressed in keloid and hypertrophic scars and increased POSTIN expression affects the proliferation, collagen synthesis, migration, and invasion of keloid fibroblasts under hypoxic conditions." (PMID 35872873, 2022). "Another prominent protein found in keloid ECM is periostin, a stromal cell protein that promotes keloid formation by activating the RhoA pathway to promote TGF-β1 secretion." (PMID 35614943, 2022).
keloid (continued). "Despite clear differences in keloids and hypertrophic scars, both illustrate elevated periostin expression." (PMID 34295891, 2021). "One of the characteristics of the mesenchymal fibroblasts in keloid is the high expression of secretory proteins such as POSTN, COMP, COL11A1, ASPN, and COL5A2." (PMID 34140509, 2021). "Our studies indicate that mesenchymal fibroblasts are important for the overexpression of collagens in keloid through POSTN." (PMID 34140509, 2021). "Many authors have reported that periostin is abnormally elevated in hypertrophic scars and keloids compared to normal tissues and implicates periostin as a possible therapeutic target in the treatment of hypertrophic scars and keloid." (PMID 29498630, 2018). "Our previous study demonstrated that the expression of periostin is upregulated in keloids compared with hypertrophic scars and normal skin tissue." (PMID 25369801, 2015). "In conclusion, the present study revealed that the expression of periostin was increased in human keloid tissue and correlated with blood vessel density." (PMID 25369801, 2015). "Appropriate regulation of periostin is required throughout the repair process as dysregulation of periostin leads to excess proliferation, including the formation of hypertrophic scars and keloids or even tumors." (PMID 25369801, 2015). "The expression of periostin was upregulated and the vessel density was higher in human keloids compared with normal tissue, observed following staining with CD31 and CD105." (PMID 25369801, 2015). "The protein level of periostin was 2.3-fold higher in the keloid tissue compared with the normal skin." (PMID 25369801, 2015). "The presents study demonstrated that the level of periostin and blood vessel density were higher in human keloid tissue compared with normal tissue and a positive correlation was observed between periostin level and blood vessel density." (PMID 25369801, 2015). "Our previous study found that periostin was highly expressed in keloids and gradually increased between normal skin and hypertrophic scars to keloids." (PMID 25369801, 2015). "In contrast, COL1A1, COL1A2, and POSTN expression levels were significantly increased in wounded keloid ESS." (PMID 22536458, 2012). "Notably, POSTN+ mesenchymal fib showed a higher expression proportion in keloid samples compared to normal ones." (PMID 39902627, 2025). "In addition, the high POSTN expression in the keloid group was similar to findings in the previous study." (PMID 40742741, 2025). "Additionally, we found that both IGFBP2+ fibs and POSTN+ mesenchymal fibs display strong cellular communication signals with endothelial cells in both keloid and normal skin tissues." (PMID 39902627, 2025). "Moreover, to investigate changes in the expression of the two mechanosensitive channels, we compared the POSTN expression previously reported to increase keloids with PIEZO1 and PIEZO2 expression in the same 30‐case dataset." (PMID 40742741, 2025). "Enrichment and cell–cell communication analyses revealed that POSTN‐positive mesenchymal fibroblasts (POSTN+ mesenchymal fibs) are more prevalent in keloids and exhibit higher transforming growth factor β (TGF‐β) signalling activity, potentially playing a central role in excessive fibrosis." (PMID 39902627, 2025). "Indeed, the upregulated PIEZO2 gene expression in keloids aligns with earlier studies demonstrating higher expression of COL1A2 and POSTN in keloids than in normal skin tissue." (PMID 40742741, 2025). "Similarly, POSTN signalling is enhanced in mesenchymal fibroblasts, highly expressed in keloid and hypertrophic scar tissue, and positively correlated with TGF‐β1 expression." (PMID 39902627, 2025). "Both POSTN+ mesenchymal fibs and IGFBP2+ fibs were associated with the ECM in keloids." (PMID 39902627, 2025).
keloid (continued). "Our research not only revealed the ubiquity and activity of POSTN‐positive mesenchymal fibroblasts in keloids but also discovered the predominant role of IGFBP2‐positive fibroblasts in normal skin and their potential significance in the process of anti‐fibrotic therapy." (PMID 39902627, 2025). "In the present study, POSTN was found to be significantly upregulated in keloids." (PMID 41278551, 2025). "Further functional research suggested that mesenchymal cells may induce the overexpression of collagen in keloid scars via POSTN." (PMID 35722137, 2022). "However, hypertrophic scars contain thick collagen bundles with high levels of periostin surrounding the cells, whereas keloid scars lack cells with periostin around them." (PMID 34295891, 2021). "OC-20 inhibited the increased expression of collagen I and III in fibroblasts of CD266+/CD9− supernatant treatment significantly, suggesting that the mesenchymal fibroblasts promoted collagen synthesis of the other fibroblasts in keloid partially through POSTN." (PMID 34140509, 2021). "The present study aimed to examine the effect of periostin on angiogenesis in keloids." (PMID 25369801, 2015). "Therefore, periostin promotes angiogenesis to directly affect the development of keloids and is, therefore, a novel pro-angiogenic factor involved in angiogenesis in keloids." (PMID 25369801, 2015). "Subsequently, the present study investigated whether the periostin that is secreted by keloid fibroblasts (KFs) affects endothelial cell migration and angiogenesis and aimed to elucuidate the underlying mechanism in vitro." (PMID 25369801, 2015). "In conclusion, these data suggested that upregulation in the level of periostin may promote angiogenesis directly and indirectly in keloids and may be a key factor in keloid development." (PMID 25369801, 2015). "Periostin may, therefore, be a promising therapeutic target in the treatment of keloids and other angioproliferative diseases." (PMID 25369801, 2015). "In keloids, the proportion of mesenchymal fibroblasts is significantly higher than in normal scars, and these cells express higher levels of ossification‐related genes such as cartilage oligomeric matrix protein (POSTN) and collagen‐related genes like type I collagen α1 (COL1A1)." (PMID 39902627, 2025). "Consequently, inhibiting mesenchymal fibroblasts by blocking the TGFβ pathway or targeting POSTN might potentially serve as viable therapeutic approaches for treating keloid." (PMID 37809065, 2023). "The validation of the screened hub genes in the GEO dataset revealed that three hub genes—BMP4, POSTN, and WNT5A—were significantly differentially expressed in keloid tissue compared to normal skin tissue." (PMID 41278551, 2025). "We then investigated the effects of POSTN+ mesenchymal fibs and IGFBP2+ fibs on collagen expression in keloid fibroblasts." (PMID 39902627, 2025). "We found that the expression levels of BMP4, POSTN, and WNT5A were significantly higher in keloid samples compared to control samples, as identified through differential gene screening and validated using an independent dataset." (PMID 41278551, 2025). "Single‐cell analysis of TGF‐β signalling indicates that immune cells are the primary signal emitters in keloids, while MCTP1+ fibs and POSTN+ mesenchymal fibs mainly act as mediators and receivers." (PMID 39902627, 2025). "POSTN and WNT5A demonstrated perfect discriminative ability with AUC values of 1.000, indicating their high specificity and sensitivity in identifying keloid tissue." (PMID 41278551, 2025). "Additionally, further investigation into the activation mechanisms of POSTN+ mesenchymal fibroblasts, as well as the interaction mechanisms between fibroblast subpopulations and other cell types, especially at various stages of keloid development, is necessary." (PMID 39902627, 2025). "A crucial marker for mesenchymal fibroblasts is periostin (POSTN), which is observed at high levels in keloids." (PMID 39519131, 2024).
keloid (continued). "Among them, the number of mesenchymal fibroblasts (a type of myofibroblasts) characterized by collagen type XI alpha 1 chain (COL11A1) and periostin (POSTN) expression, was increased in keloid compared with normal scars." (PMID 38622256, 2024). "Fibroblasts isolated from keloid tissue have elevated expressions of TGF-β1, periostin, PAI-2, and inhibin beta A compared to normal healthy tissues." (PMID 37446165, 2023). "Genes involved in extracellular matrix formation including COL1A1, COL3A1, POSTN, COL1A2, FN1, and ASPN were significantly upregulated in keloid compared to the normal skins." (PMID 35990663, 2022). "Blocking the interactions by using POSTN neutralizing antibodies inhibited the increase of collagens in other fibroblasts treated with mesenchymal fibroblast supernatant, indicating that these interactions are important for keloid collagen overexpression and may serve as therapeutic targets." (PMID 34140509, 2021). "We observed increased cellular infiltrates in keloid tissues, including T-cells, dendritic cells, mast cells, as well as greater IL-4rα+, CCR9+, and periostin+ immunostaining." (PMID 33329590, 2020). "Conditioned medium from keloid fibroblasts (KFs) promoted the migration and tube formation of human umbilical vein endothelial cells (HUVECs) compared with normal fibroblasts and this effect may have been abrogated by the short hairpin RNA knockdown of periostin." (PMID 25369801, 2015). "Therefore, periostin may promote angiogenesis in keloids and be a key factor in their development." (PMID 25369801, 2015). "Furthermore, we examined periostin expression in the lesional skin from patients with other skin fibrotic diseases (keloid and hypertrophic scar), and found that periostin appeared to be expressed more strongly in lesional skin tissue of scleroderma than in those of keloid and hypertrophic scar." (PMID 22911870, 2012). "As expected, we show herein the enhanced expression of periostin in lesional skin from patients with scleroderma and in BLM-induced sclerotic mouse skin, compared with hypertrophic scar, keloid, normal skin and PBS-treated mouse skin." (PMID 22911870, 2012). "Subsequent network topology analysis through CytoHubba identified six hub genes (IL6, POSTN, VCAN, COL11A1, HAPLN1, TNC) via three methods of calculation respectively (Closeness, Degree and EPC), representing key regulatory nodes in the keloid." (PMID 41544047, 2026). "Interestingly, we found that the POSTN-ITGAV;ITGB5 interactions between mesenchymal and other fibroblasts were significantly increased in keloid compared to normal scar." (PMID 34140509, 2021). "A marked positive correlation was observed between the level of periostin protein and the blood vessel density in the CD31 staining (r=0.711, P<0.01) and a weak correlation was observed following CD105 staining (r=0.251, P<0.01) in keloid tissue." (PMID 25369801, 2015). "Periostin also affected the expression of VEGF and Ang-1 in the KFs and periostin may be a promising therapeutic target for treatment of keloids and other angioproliferative diseases." (PMID 25369801, 2015). "In the present study, the increased periostin level in keloids was correlated with the expression of CD31 and CD105, which suggested that periostin may promote angiogenesis in keloids." (PMID 25369801, 2015). "However, expression of COL11A1 and POSTN is also observed during the normal wound healing process and is not specific to keloid formation." (PMID 38622256, 2024). "The expression of periostin and the vascular endothelial-cell markers CD31 and CD105 were examined using immunohistochemistry to examine whether the expression of periostin and the density of blood vessels differed between the keloid and the normal skin tissue." (PMID 25369801, 2015).
keloid (continued). "In vitro phenotypic assessment using the intact C1Q complex showed that C1Q increased ACTA2 expression in primary keloid fibroblasts, whereas RAP attenuated this effect; COL1A1 and POSTN showed no consistent induction." (PMID 42278663, 2026).